RAC1 (Rac family small GTPase 1)
Diseases named in the same sentence as RAC1 in open-access papers (continued):
Sharing a sentence is not in itself a finding about the gene and the disease.
melanoma (206 papers, 2010 to 2026). A malignant, usually aggressive tumor composed of atypical, neoplastic melanocytes. "Large-scale genomic sequencing of melanoma has identified bona fide activating mutations in RAC1, which are associated with resistance to BRAF-targeting therapies." (PMID 39636745, 2025). "A recent report studying RAC1P29S in YUMM1.7 melanoma cells found that this RAC1 mutation sensitizes the tumor cells to anti-PD1 therapy, distinct from our findings here." (PMID 41160695, 2025). "As of today, most functional studies on RAC1 mutations are focused on the melanoma-prevalent P29S hotspot mutation (found in ~5–8% of melanoma patients), even though other RAC1 mutations have been reported in various cancers." (PMID 39941730, 2025). "To validate our biochemical data and expand its applicability to melanoma, we examined RAC1P29S activity in IGR1 human melanoma cells, which harbor both the RAC1 P29S and BRAF V600K mutations endogenously." (PMID 41034404, 2025). "Multiple cancer-associated mutations in Rac1 have been identified, including the melanoma hotspot mutation P29S." (PMID 41360259, 2025). "The proline 29 to serine (P29S) mutation in RAC1 is the third most common hotspot mutation in melanoma, following BRAF V600E and neuroblastoma RAS viral oncogene homolog (NRAS) Q61R." (PMID 41034404, 2025). "Lastly, melanoma and endometrial xenograft models bearing endogenous RAC1-amplification and RAC1-A159V mutation were also sensitive to EHop-016 targeting." (PMID 39941730, 2025). "Our data suggest that p110β inhibition selectively sensitizes cells to MEK inhibition in the subset of PTEN-deficient melanomas harboring hyperactivation of RAC1 signaling, or broader dysregulation of the PREX2/RAC1/PI3Kβ axis." (PMID 39636745, 2025). "The RAC1P29S hotspot mutation, which is prevalent in melanoma, drives tumorigenesis by promoting the persistent activation of RAC1." (PMID 41034404, 2025). "The specific mutation RAC1 R29S, identified in up to 9% of sun-exposed melanomas, results in its constitutive activation promoting downstream signaling, driving cancer cell proliferation and survival, cytoskeleton remodeling, and invasion." (PMID 40872623, 2025). "Mutations in the monomeric GTPase gene RAC1 are the third most common hotspot mutation in melanoma after BRAF and NRAS mutations." (PMID 41109929, 2025). "RAC1 mutations are insufficient to drive melanoma and are almost always found with other activating MAP kinase hot spot mutations, most frequently NRAS (47%), BRAF, or NF1." (PMID 40396280, 2024). "RAC1 mutations are present in 2–9% melanomas, usually in association with activation mutations in BRAF or NRAS, or inactivating mutations in NF1." (PMID 40396280, 2024). "The Rac1 mutation occurred in both Braf and Nras mutant melanomas, but a higher percentage of Braf/Nras wild type melanomas possess the Rac1P29S mutation." (PMID 36875127, 2023). "Recently, mutations in Rho GTPases in multiple cancer types have been identified and characterized, most notably the Rac1(P29S) mutation, which has been shown to be a driver mutation in melanoma." (PMID 37114375, 2023). "The paradoxical activation of the MAPK/ERK pathway through p.Pro29Ser mutation in the RAC1 gene is a recognized mechanism responsible for primary/acquired resistance in melanoma." (PMID 36901733, 2023). "Previous studies have shown that upregulated CSDE1 expression was associated with melanoma through elongation of the oncogene Rac1." (PMID 35490208, 2022). "Given the selective sensitivity to SRCi, divergence in RAC1 utilization, and association with drug resistance in de-differentiated melanomas, we aimed to create a practical strategy to determine melanoma differentiation status." (PMID 36271142, 2022). "Later, the occurrence of a point mutation in human RAC1 was revealed in a study of the mutational landscape in melanoma tumors." (PMID 35454871, 2022).
melanoma (continued). "P29S in Rac1 was initially identified as one of the major somatic mutations in human melanoma, shown to enhance Rac1 binding to various effector proteins, including PAK1 (p21 protein activated kinase 1), MLK3 (mixed-lineage kinase 3), and the WRC14,22,23." (PMID 36114192, 2022). "We found that RAC1 is a driver of growth and innate drug resistance to BRAFi in some melanoma cell lines and that the reliance on RAC1 was associated with the de-differentiated phenotypic state." (PMID 36271142, 2022). "Marginally, a 3′UTR germline mutation in RAC1 (rs9374) was identified as the most significant biomarker in predicting toxicity across cancers and within both the melanoma and other cancer subgroups." (PMID 35115362, 2022). "Additional functionally relevant Rac1 mutations include Ala159 (predominantly in head and neck cancers), Asn92, (melanoma, myeloma and sarcoma), Cys157 and the canonical Gly12 (mainly prostate cancer) and Gly61 (testicular germ cell cancer)." (PMID 34440759, 2021). "In an elegant study, Watson and colleagues demonstrated that the presence and overexpression of the RAC1 mutation in melanoma cell lines confer resistance to BRAF inhibitors and that silencing RAC1 restores sensitivity." (PMID 34638434, 2021). "RAC1P29S is the third most commonly mutated codon in human cutaneous melanoma, after BRAF V600 and NRAS Q61, and one of the most prominent driver mutations in RAC1 with a frequency of approximately 5% and up to 10% in chronically sun-exposed melanomas." (PMID 34827551, 2021). "The RAC1 P29S mutation works along with BRAF to promote melanoma initiation and cause resistance to BRAF inhibitors." (PMID 34804979, 2021). "The RAC1 P29S mutation was identified in both primary (9.2%) and metastatic (8.6%) melanoma, indicating that it is present early in carcinogenesis." (PMID 34804979, 2021). "Compared with Rac1 WT, melanoma cells with Rac1(P29S) mutations express high levels of PD-L1 and therefore have the ability to evade immune surveillance." (PMID 34079763, 2021). "RAC1 was identified as the third most common recurrent mutation in melanomas and can be found in 4–7% of all patients." (PMID 33511023, 2021). "The RAC1 P29S mutation is more frequent in melanomas BRAF and NRAS wild-type and occurs early in tumorigenesis." (PMID 34123788, 2021). "Recently, whole-exome sequencing of human melanoma samples revealed the existence of activating mutations affecting codons 28 and 29, such as RAC1 (F28L) and RAC1 (P29S)." (PMID 34638434, 2021). "In fact, up to 9.2% of sun-exposed melanoma contain a RAC1P29S mutation that replaces the proline 29 for a serine in the switch I domain of RAC1 that is responsible for nucleotide and effector binding." (PMID 34503171, 2021). "The RAC1 P29S mutation is a frequent UV-signature mutation that is found in 9.2% of sun-exposed melanomas." (PMID 34804979, 2021). "The identification of activating mutations in RAC1 in samples obtained from melanoma and other malignancies have further supported the crucial driver role of this Rho GTPase in cancer progression." (PMID 34943902, 2021). "For these experiments, we tested Rac1 mutants containing the constitutively active mutation Q61L or the tumor-derived, fast-cycling mutation P29S, highly prevalent in melanomas." (PMID 33914026, 2021). "This emergent mutation (P34R) differs from other RAC1 resistance mutations so far found in melanoma or other tumor types, e.g., RAC1 (P29S)." (PMID 34638434, 2021). "This capacity of activating MAPK pathway also plays a role in protecting melanoma cells with RAC1 and BRAF mutations from apoptosis when treated with RAF inhibitors." (PMID 34827551, 2021). "The mutations in RAC1 (e.g., P29S and N92I) identified in melanoma increase the proportion of activated RAC1 due to the enhanced GDP/GTP-exchange reactions associated with accelerated GDP dissociation." (PMID 34801548, 2021).
melanoma (continued). "HOXD8 and RAC1 mutations have also been shown to give melanomas primary resistance to targeted therapies." (PMID 35008286, 2021). "Particularly, the P29S substitution is the most common RAC1 mutation found in malignant melanomas, inducing RAC1 spontaneous activation through the constitutive GDP/GTP nucleotide exchange." (PMID 33072757, 2020). "Daniela Araiza-Olivera and her colleagues explored potential signaling pathways linked to Rac1 driven malignant melanoma during zebrafish embryonic development." (PMID 33302361, 2020). "While our results indicate that the loss of CUL3 leads to the activation of RAC1 in melanoma cells and confers resistance to BRAFi, the exact mechanism leading to RAC1 activation in CUL3KD cells is still unclear." (PMID 32346533, 2020). "NeoANT-HILL was applied in The Cancer Genome Atlas (TCGA) melanoma dataset and found several putative neoantigens including ones derived from the recurrent RAC1:P29S and SERPINB3:E250K mutations." (PMID 32087727, 2020). "The somatic Rac1 mutation P29S has been discovered as an oncogenic driver in the melanoma and other cancers." (PMID 32193458, 2020). "WES studies led to the discovery of a hotspot mutation (P29S) in RAC1 gene, defining it as the most frequent driver mutation in sun-exposed melanomas, with a frequency of 5–7%." (PMID 32850962, 2020). "Despite mutations in Rho GTPase-encoding genes representing uncommon events, it was described that RAC1-activating mutations are present in approximately 4–9% of melanomas." (PMID 33072757, 2020). "Although the presence of the Rac1 mutation in melanoma, it is more often that tumors show altered expression and/or mutations in upstream regulatory proteins, such as GEFs." (PMID 32351958, 2020). "Of relevance, a somatic mutation of RAC1 has been found as an oncogenic driver in melanoma, head and neck and prostate cancers." (PMID 33298895, 2020). "Recently, two independent whole-exome sequencing studies revealed a novel gain-of-function mutation of Rac1 in sun-exposed melanomas, being the most frequently observed somatic mutation after BRAF and NRAS mutations." (PMID 32351958, 2020). "The somatic mutation of Rac1 has been discovered to function as a driving factor of malignancy in melanoma and other cancers." (PMID 32193458, 2020). "High levels of PD-L1 in patients with RAC1 P29S mutations compared to wild-type RAC1 melanoma samples from the TCGA cohort were observed." (PMID 32850962, 2020). "Concerning treatment, in vitro studies have shown that melanoma cell lines harboring the RAC1 P29S mutation are resistant to BRAF and MEK inhibitors, but its role in conferring this resistance is still to be elucidated." (PMID 32850962, 2020). "A recent study demonstrated that melanoma cells carrying the RAC1P29S mutation exhibit an augmented engagement of PAK1 (an immediate downstream effector of RAC1) in the presence of the RAC1P29S mutant and are thus highly sensitive to the PAK1 inhibitor." (PMID 32545340, 2020). "This discovery makes RAC1 the third most commonly mutated (somatic) proto-oncogene in melanoma after BRAF and NRAS." (PMID 31027363, 2019). "The potential importance of RAC1 function in melanoma is further underlined by the discovery of frequent alterations in PREX2, and to a lesser extent PREX1, which are guanine nucleotide exchange factors for RAC1." (PMID 31257073, 2019). "The recurrent point mutation Rac1/P29S has been implicated in melanomas and has been shown to have significantly increased intrinsic GDP/GTP exchange activity." (PMID 31330900, 2019). "A recurrent gain-of-function mutation in RAC1 gene (P29S) has been identified in melanomas by a genome-wide analysis." (PMID 31248017, 2019). "Despite frequent mutational activation of RAC1 and its regulators in melanoma, the functional implications for the disease are poorly understood." (PMID 31257073, 2019).
melanoma (continued). "Recent studies, enabled by next-generation exome sequencing, report activating point mutations in RAC1 GTPases as driver mutations in melanoma, as well as breast, head, and neck cancers." (PMID 31027363, 2019). "RAC1 activation and mutation are closely related to the onset of melanoma and non-small cell lung cancer." (PMID 31873123, 2019). "Both overexpression and mutation have been described in cancer, most notably, RAC1 P29S mutation is a recurrent mutation in melanoma." (PMID 29329780, 2018). "To conclude, our initial analyses revealed an increased risk of melanoma associated with rs10951982 (RAC1), and a decreased risk associated with rs8031 (SOD2)." (PMID 29342889, 2018). "In multivariate logistic regression, RAC1 rs10951982 (OR 6.15, 95% CI: 2.98 to 13.41; p < 0.001) remained significantly associated with increased risk of melanoma." (PMID 29342889, 2018). "High MITF concomitantly suppressed activity of RAC1, a kinase mutated in a subset of melanomas 43, and suppression of RAC1 activity was required to reduce invasiveness." (PMID 29369499, 2018). "Overall, of the three significant SNPs after adjustment against age, sex, family history and life time sun burn history, the minor allele of RAC1 rs10951982 (the A allele) showed a consistent role with an increase ROS and thus increased melanoma risk." (PMID 29342889, 2018). "Because the N92I RAC1 mutation is activating, we would expect it to have a similar effect to the P29S mutation in melanoma." (PMID 29329780, 2018). "Select point mutants are the primary cause of constitutive Rac1 activation in some cancer types (melanoma, lung and germ cell cancers)." (PMID 30261690, 2018). "A relatively extensive mutation analysis of sun-exposed melanomas resulted in the identification of a novel point mutation in Rac1, as Rac1/P29S." (PMID 30544828, 2018). "The P29S mutation was identified as one of the major somatic mutations in melanoma, and was shown to increase the affinity of Rac1 for the effectors PAK1 (p21 protein activated kinase 1) and MLK3 (mixed-lineage kinase 3)." (PMID 28949297, 2017). "Unlike Ras proteins, activating mutations in Rac1 rarely drive the activation of the Rac1 pathway, with a recently characterized activating mutation being Rac1 P29S, identified in melanoma." (PMID 28410221, 2017). "RAC1 has been recognized as a frequently mutated melanoma gene by next-generation sequencing studies." (PMID 28265786, 2017). "In adition, GRIN2A and RAC1 mutations were also associated with chronically sun-exposed melanomas [p = 0.011; OR = 5.9 (1.5–23.2) and p = 0.026; OR = 3.2 (1.1–9.2), respectively]." (PMID 28356599, 2017). "RAC1 mutations are present in all melanoma subtypes, which can be explained by its position at the crossroads of KIT/NRAS/BRAF/MAPK signaling and the PI3K/PTEN/AKT axis." (PMID 28265786, 2017). "A more recent biological insight into the P29S mutation showed increased expression of PD-L1 in Rac1 P29S melanoma patients compared to Rac1 wild type or other Rac1 mutants." (PMID 27104658, 2016). "Whole-exome sequencing was performed in melanoma samples and 5% of them were found to harbour missense mutations in the Rac1 gene, making Rac1 the third most highly mutated gene in melanoma (after BRaf and NRas)." (PMID 27104658, 2016). "In particular, the discovery of a recurrent Rac1 mutation in melanoma has significantly altered the perception of the role of Rho GTPases as drivers of oncogenic progression." (PMID 27104658, 2016). "Exposing SPARC-deficient cells to a dominant negative form of Rac1 promoted cells’ transition to a more aggressive phenotype that resembled control melanoma cells." (PMID 26248315, 2015). "Rac1 has been identified as the third most commonly mutated protooncogene (P29S substitution) in melanoma after BRAF and NRAS." (PMID 26079945, 2015).
melanoma (continued). "It was demonstrated a landscape of driver coding mutations associated with UV-light-induced damage in human melanoma, which include oncogenes as Ras, B-Raf and Rac1." (PMID 24358134, 2013). "Recently, two independent groups demonstrated that Rac1 is the third driver gene more frequently mutated in melanomas after Ras and B-Raf." (PMID 24358134, 2013). "Nonetheless, larger cohort studies are still missing, and the significance of RAC1 mutations in melanoma and their impact on systemic treatment strategies remain unclear." (PMID 40872623, 2025). "In A375 melanoma cells, this spontaneous Rac1-driven resistance pathway is associated with an undifferentiated gene expression profile, activation of a YAP/TAZ gene expression signature, and resilience to pharmacological inhibition and genetic depletion of MEK1/2." (PMID 41109929, 2025). "The RAC1 P29S mutation is responsible for oncogenic resistance in melanoma treatment with BRAFi." (PMID 40872623, 2025). "Lastly, RAC1-amplified melanoma and RAC1-A159V-mutated endometrial cancer may also be druggable with EHop-016." (PMID 39941730, 2025). "In the TCGA melanoma dataset where primary tumors were sequenced, RAC1-amplification was found in 3.27% (12/367) of cases, whereas RAC1 mutations were found in 5.4% (20/367) of cases, with the majority being the well-known melanoma-prevalent P29S hotspot mutation (TCGA-SKCM Firehose, n = 367)." (PMID 39941730, 2025). "RAC1 mutations are rare in melanomas and most often occur in cutaneous ones." (PMID 37373134, 2023). "In addition to this, RAC1 mutated melanomas have been linked to resistance to therapy and decreased relapse-free survival." (PMID 37373134, 2023). "Although RAC1 inhibitor drugs are not currently available in clinical practice, SRF/MRTF inhibitors in combination with BRAF inhibitors have recently been shown to be effective in the treatment of BRAF mutant melanoma cells with a co-occurring RAC1 P29S mutation." (PMID 36901733, 2023). "Following mutations in Braf V600 and Nras Q61, Rac1 P29 is the third most commonly mutated protooncogene in cutaneous melanomas and with up to 9% of sun-exposed melanomas carrying this mutation the most common cancer-associated recurrent missense mutation among the family of small Rho GTPases." (PMID 36875127, 2023). "Interestingly, in sun-exposed melanomas, the third most common recurring somatic mutation was a serine for a proline mutation in RAC1." (PMID 35454871, 2022). "Notably, whole genome sequencing experiments have revealed that RAC1 is frequently mutated in melanoma patients." (PMID 34503171, 2021). "RAC1 is a Rho GTPase family member which has shown to be mutated (RACP29S) in 4% of melanomas." (PMID 34066022, 2021). "Exosome-sequencing efforts have revealed Rac1 activating mutations in malignant melanoma patients." (PMID 34440759, 2021). "This could have important implications for cancers where RAC1 pathways are disrupted or enhanced, such as in melanomas where RAC1 activating mutations are considered to be drivers." (PMID 34165494, 2021). "Taking melanoma as an example, Rac1 is an important somatic-driven mutation gene in melanoma." (PMID 34079763, 2021). "Indeed, The Cancer Genome Atlas (TCGA) data shows that RAC1 is upregulated or mutated in over 10% of human cancers, including melanoma, glioblastoma, skin, esophageal, gastric, bladder, head and neck, liver, pancreatic, and prostate carcinomas." (PMID 34827551, 2021). "RAC1 mutations such as P29S have been shown to cause resistance to BRAF inhibitors in melanoma, but the consequences of a P34R mutation are unknown." (PMID 34638434, 2021). "To analyze whether impaired Cdc42 signaling is responsible for the reduced invasion caused by WNT5A knockdown in these melanoma cells, we stimulated the cells with a Cdc42 and Rac1 activator." (PMID 33969605, 2021).